RNU6-179P (RNA, U6 small nuclear 179, pseudogene)
Gene: Small nuclear RNA gene on chromosome 1 (154,039,916 to 154,040,022, reverse strand). Ensembl gene ENSG00000200220.
Homologues: Orthologues: chimpanzee U6 (94% identical), macaque U6 (89% identical), pig U6 (84% identical), pig U6 (76% identical), dog U6 (75% identical), rabbit U6 (75% identical), guinea pig U6 (74% identical). Paralogues in human: RNU6-43P (85% identical), RNU6-1091P (84% identical), RNU6-1309P (84% identical), RNU6-175P (84% identical), RNU6-24P (84% identical), RNU6-35P (84% identical), RNU6-727P (84% identical), RNU6-1031P (83% identical), RNU6-1094P (83% identical), RNU6-1141P (83% identical), RNU6-1152P (83% identical), RNU6-11P (83% identical), and 1286 more.